MYC (MYC proto-oncogene, bHLH transcription factor)
Diseases named in the same sentence as MYC in open-access papers (continued):
Sharing a sentence is not in itself a finding about the gene and the disease.
ovarian carcinoma (continued). "c-MYC is repressed upon restoration of p150 to ovarian carcinoma cells." (PMID 23029531, 2012). "Whether these observations apply to MYC-addicted ovarian cancer cells remains to be seen." (PMID 40487451, 2025). "Thus, we also asked whether there is a correlation between MYC amplification and the mutational status of the CDK12/13 genes in ovarian cancer." (PMID 37202753, 2023). "In addition, targeting c-MYC also sensitizes ovarian cancer cells to chemotherapy." (PMID 36765581, 2023). "The results show that ovarian cancer in the high-risk group may be involved in epithelial-mesenchymal transition, KRAS signaling pathway, TNF NFKB signaling pathway, and angiogenesis, while the low-risk group is negatively associated with E2F and MYC pathways." (PMID 37859811, 2023). "Furthermore, MYC, EGFR, CCND1 exhibited close association with chemotherapeutic response to platinum and showed a high expression in ovarian cancer tissues and platinum-resistant ovarian cancer cells." (PMID 35739532, 2022). "Thus, we inferred that celastrol could regulate c-MYC to alter the tumor microenvironment in dealing with ovarian cancer." (PMID 35370699, 2022). "Furthermore, we found that silencing HJURP could modulate cisplatin sensitivity of ovarian cancer via MYC/WEE1 axis." (PMID 35173547, 2022). "Notably, c-MYC contributes to the regulation of USP39 transcription in ovarian cancer." (PMID 33731694, 2021). "In addition, miR-145 inhibits glutamine metabolism in ovarian cancer through c-MYC/GLS1 pathways." (PMID 33718147, 2021). "Importantly, MYC transcriptionally upregulated HMGA1P6 as well as HMGA131 in ovarian cancer." (PMID 32127525, 2020). "Importantly, HMGA1P6 was transcriptionally activated by oncogene MYC in ovarian cancer." (PMID 32127525, 2020). "Moreover, recent reports have shown that suppression of MYC via inhibition of CDK7, CDK12 and CDK13 may be an effective treatment for MYC-dependent ovarian cancer." (PMID 32570740, 2020). "Additionally, MYC autoantibodies have been reported in ovarian cancer." (PMID 32092936, 2020). "Clinically, BRD4 is highly expressed in ovarian cancer and independently predicts poor survival, outperforming FOXM1 and MYC." (PMID 41820523, 2026). "Further investigation into pathways demonstrated that FAM111B was linked to the tumor proliferation signature (R = 0.51, P < 0.001), MYC pathway (R = 0.32, P < 0.001), and the EMT (R = 0.20, P < 0.001) in ovarian cancer." (PMID 40781291, 2025). "Ovarian cancer EMT and proliferation are driven by MYC, which is stabilized from ubiquitin-mediated proteolysis by serine-62 phosphorylation of MYC by active ERK1/2." (PMID 39858588, 2025). "The current study also found a significant number of binding sites for HSF1 and MYC in ovarian cancer cells wherein the binding peaks are overlapping, which would be consistent with previous reports suggesting that HSF1 and MYC form protein complexes with DNA." (PMID 39831777, 2025). "Here we show increased TF activity of MYC, a commonly amplified TF in HGSOC responsible for promotion of uncontrolled cellular proliferation in the proliferative subtype of ovarian cancer." (PMID 39574035, 2024). "That premise is supported by our finding of upregulated MYC target gene expression in PKA-activated adrenal and ovarian cancers in the TCGA." (PMID 36692000, 2023). "c-MYC and its paralogues MYCN and MYCL are among the most frequently amplified and/or overexpressed oncoproteins in ovarian cancer." (PMID 36765581, 2023).
ovarian carcinoma (continued). "Dual targeting of FAK and MYC by VS-6063 and JQ1 resulted in cell cycle arrest and cell death of ovarian cancer cells in vitro." (PMID 36765581, 2023). "Collectively, these findings emphasize the need to integrate the multidimensional data incorporating the complexity of c-MYC signaling at the protein level, localization, as well as PTM status, to define the relationship between c-MYC and ovarian cancer." (PMID 36765581, 2023). "Another molecule, JQ1, targeting c-MYC and BRD4, suppresses ovarian cancer cell proliferation and induces apoptosis." (PMID 36765581, 2023). "Many cancers, including ovarian cancer, are addicted to c-MYC signaling, which has served as the justification for targeting c-MYC." (PMID 36765581, 2023). "Indirect inhibition of c-MYC by the CDK7 and CDK12/13 inhibitor THZ1 repressed tumor growth in patient-derived xenograft models of ovarian cancer." (PMID 36765581, 2023). "MYC, EGFR, and CCND1 expressed at higher protein levels in ovarian cancer patients than in normal ovarian tissues." (PMID 35739532, 2022). "In ovarian cancer, c-MYC, CDC37, and FN1 play essential roles in the initiation and progress of ovarian cancer." (PMID 35370699, 2022). "Results exhibited positive correlations of MYC, EGFR, and CCND1 with overall survival of ovarian cancer patients after chemotherapy." (PMID 35739532, 2022). "Combined with results of PPI analyses and TCGA database, MYC, EGFR, and CCND1 were determined to be the key genes correlated with the chemoresistance affected by CAFs in ovarian cancer." (PMID 35739532, 2022). "Correlation analysis was performed based on the expression of MYC, EGFR, and CCND1 in the TCGA-ovarian cancer dataset." (PMID 35739532, 2022). "Here, the authors found that TRIM47 knockdown reduced STAT3 phosphorylation at Tyr705 in both cultured and xenografted ovarian cancer cells, followed by reduced expression of the STAT3 target genes MCL-1, MMP2, and c-MYC." (PMID 36288633, 2022). "First, a meta-analysis based on the TCGA database found that PD-L1 expression was closely correlated with MYC, SOX2, and SNAI1 in the endometrial and ovarian cancer data sets." (PMID 36582540, 2022). "In patient-derived xenografts models from patients with heavily pre-treated ovarian cancer, THZ1 (a chemical that inhibits CDK7, CDK12, and CDK13) repressed MYC expression and suppressed tumor growth." (PMID 33686962, 2021). "Ovarian cancer and triple-negative breast cancer (TNBC) share common genomic features including MYC copy-number amplification." (PMID 33671595, 2021). "For example, c-MYC directly stimulates transcription of DANCR, an oncogenic lncRNA upregulated in ovarian cancer." (PMID 33718147, 2021). "By targeting BRD4 and c-MYC, JQ1 suppresses ovarian cancer cell proliferation and induces apoptosis." (PMID 33718147, 2021). "Mechanistically, MBZ was shown to inhibit multiple cancer-related signal pathways including ELK/SRF, NFKB, MYC/MAX, and E2F/DP1 in cisplatin-resistant ovarian cancer cells." (PMID 34232919, 2021). "Mechanistically, MBZ was revealed to inhibit multiple cancer-related signal pathways including ELK/SRF, NFKB, MYC/MAX, and E2F/DP1 in cisplatin-resistant ovarian cancer cells." (PMID 34232919, 2021). "MYC, which is commonly overexpressed in HGSOC and ovarian cancer cell lines was predicted with two binding sites on HMGA1P6 promoter region." (PMID 32127525, 2020).
ovarian carcinoma (continued). "As shown in the model, calcitriol suppresses ovarian cancer cell growth, migration and invasion by down-regulating CCAT2 and repressing its interaction with TCF4, decreasing CCAT2/TCF4 binding to the MYC promoter." (PMID 32230936, 2020). "MYC, EGR1, and miR-130a-3p were hubs in our integrative analysis of ovarian CSC-enriched SFCs, suggesting that ovarian cancer SFCs display a stem cell identity with the quiescent phenotype where adhesion- and cell cycle-related genes were suppressed." (PMID 32046751, 2020). "In ovarian carcinoma, KPNA2 promoted cell proliferation and G1/S cell cycle transition through increased levels of MYC." (PMID 32512858, 2020). "Moreover, ovarian cancer patients with high MYC mRNA levels tend to have lower disease-free (DFS) and the overall survival (OS) compared with their counterparts; thus, MYC may serve as a potential therapeutic target for ovarian cancers expressing high levels of this oncoprotein." (PMID 29482638, 2018). "In drug‐resistant recurrent ovarian cancer patients, RB1 had the highest frequency of copy number variations (4/10, 40%), which was followed by MYC (3/10, 30%)." (PMID 29797793, 2018). "Our meta-analysis demonstrated that PD-L1 is co-amplified along with MYC, SOX2, N-cadherin and SNAI1 in the TCGA endometrial and ovarian cancer datasets." (PMID 30283733, 2018). "Examination of the resulting network shows that RPS19, PNOC, SFRP1 and KCNJ16 are connected to other frequently altered genes, including MYC or EIF3E as oncogenes, from TCGA ovarian cancer dataset." (PMID 30255801, 2018). "MYC and RB1 had the highest frequency of copy number variations (6/21, 29%) in recurrent ovarian cancers, followed by PIK3CA (3/21, 14%)." (PMID 29797793, 2018). "The mechanism through which Let-7 favors ovarian cancer tumor progression is related to the capacity of this miRNA to target various oncogenes such as HMGA-2, MYC and K-Ras." (PMID 29389895, 2018). "In 11 patient-derived xenografts models derived from heavily pre-treated ovarian cancer patients, administration of THZ1 induces significant tumor growth inhibition with concurrent abrogation of MYC expression." (PMID 30422115, 2018). "Interaction of IGF2BP1 with c-MYC mRNA inhibits CRD-dependent mRNA decay and is correlated with poor prognosis in ovarian carcinoma." (PMID 27588393, 2016). "For example, CDKN2B and CDK4 as well as EGFR and NF1 are involved in the RB and RTK signaling pathways, respectively and the CCNE1, MYC and RAD52 module in ovarian carcinoma is involved in cell cycle." (PMID 24565034, 2013). "While MYC and PVT1 knock-downs both reduced proliferation of breast and ovarian cancer cell lines with amplification and over-expression of MYC and PVT1, knock-down of PVT1 in these lines also elicited a strong apoptotic response." (PMID 19419571, 2009). "Since MYC can also modulate apoptotic responses, comparing Bcl-xLi sensitivity in MYC-driven and non-MYC-driven ovarian cancers will be important." (PMID 40466638, 2025). "Additionally, protein transcriptomic analysis implicated FAM111B in genetic-information processing via the MYC pathway, underscoring FAM111B’s central role in ovarian cancer tumorigenesis." (PMID 40781291, 2025). "Furthermore, this regulation of MYC oxidation by IACS-010759 treatment appears to be conserved across different cancer types, as we observed a similar response in A2780 ovarian carcinoma cells." (PMID 37130865, 2023).
ovarian carcinoma (continued). "However, in breast and ovarian cancers, PVT1 acts independently of MYC, acting as an anti-apoptotic protein." (PMID 36624401, 2023). "Additionally, we observed that protein expression of MYC, EGFR, and CCND1 was notably increased in cancer tissues of ovarian cancer patients based on data from Human Protein Atlas, suggesting their important functional significance in ovarian cancer." (PMID 35739532, 2022). "In addition to MYC, CDC37, and FN1, we discovered that celastrol regulated inflammatory pathways in ovarian cancer." (PMID 35370699, 2022). "Our data suggest that ME could suppress oncogenes IGF1R and MYC by inhibiting HSP90AB1 expression, further promoting apoptosis of ovarian cancer cells." (PMID 36362498, 2022). "Our findings confirmed that HSP90AB1 overexpression could enhance the tolerance of ovarian cancer cells to chemotherapeutic agents by activating drug-resistant proteins IGF1R and MYC, affecting the prognosis of patients." (PMID 36362498, 2022). "Although a study shows that SQLE expression is independent of MYC in breast and ovarian cancers, indicating cell heterogeneity in different contexts." (PMID 33791309, 2021). "Dual targeting of FAK—an integrin-linked non-receptor tyrosine kinase—and c-MYC by VS-6063 and JQ1 inhibitors leads to cell cycle arrest and decreased cell survival in ovarian cancer cells in vitro." (PMID 33718147, 2021). "The top 5 related genes are TBP, MMP9, MYC, MAPK1, MTOR, which might play important roles in ovarian cancer." (PMID 32958005, 2020). "Importantly, metformin blocks the NGF-induced increase in c-MYC, survivin and VEGF, as well as the increase in MYC and β-catenin/TCF-Lef transcriptional activity in ovarian cancer cells." (PMID 33081077, 2020). "We here show that MYC transactivates a novel transcript, HMGA1P6 in ovarian cancer." (PMID 32127525, 2020). "Among 1680 patients with ovarian cancers, about 185 cases (11%) have the alterations in CCAT2 and 588 cases (35%) have the alterations in MYC, indicating a high incidence of the aberrant expression of CCAT2 and MYC in ovarian epithelial carcinomas." (PMID 32230936, 2020). "let-7 suppresses multiple ovarian cancer oncogenes including KRAS, HRAS, c-MYC, and HMGA-2." (PMID 32256980, 2020). "Lu et al32 reported that MYC stimulates the transcription of DANCR, and inhibition of DANCR impairs cell proliferation which could be partially rescued by p21 silencing in human ovarian cancer." (PMID 29926523, 2018). "c-MYC and KRAS were transduced into the mouse ovarian cancer cell line ID8." (PMID 27483433, 2016). "To further investigate the mechanism by which C17orf91 elicited its oncogenic role, we explored whether C17orf91 could regulate key pro-metastatic genes, such as KLF8, MYC, SNAI2, TWIST1, ZEB1 and ZEB2 in ovarian cancer." (PMID 27535740, 2016). "Some of the transcription factors driving BRCA gene expression are known oncogenes (MYC) or putative oncogenes in ovarian cancer, based on functional data and evidence of genetic activation in primary HGSOC: MYC is amplified in 30% of HGSOC, and E2F3 is amplified in about 10%." (PMID 24624361, 2014). "As KRASG12V/MYC cancer cells respond to GNE/BMS combination treatment and allow comparison with their non-cancerous progenitor cells, follow-up experiments were conducted using this cell model for ovarian carcinoma and standard concentrations of GNE (7.5 μM) and BMS (6 μM)." (PMID 40550880, 2025).
ovarian carcinoma (continued). "A recent study has identified that MYC, EGFR, and CCND1 can be amplified on extrachromosomal DNA (ecDNA) in different tumor cell lines, which may provide novel insight into identification of the mechanism of ovarian cancer progression." (PMID 35739532, 2022). "Therefore, it was speculated that MYC, EGFR, and CCND1 might affect the survival of ovarian cancer patients by mediating chemoresistance-related pathways." (PMID 35739532, 2022). "Therefore, we speculated that MYC, EGFR, and CCND1 might enhance resistance to platinum chemotherapy in ovarian cancer." (PMID 35739532, 2022). "Thus, it is not surprising that c-MYC has been considered as a potential therapeutic target against many cancer types, including ovarian cancer." (PMID 33718147, 2021). "Similar inhibitory effects by MBZ were observed for the NFKB, MYC/MAX, and E2F/DP1 reporter activities, suggesting that MBZ may exert profound inhibitory effects on cell proliferation pathways in cisplatin-resistant ovarian cancer cells." (PMID 34232919, 2021). "Whether increased mitochondrial biomass observed in ovarian cancer is correlated to MYC amplification has to our knowledge not been investigated." (PMID 30626133, 2019). "Finally, MYC transcript does not seem to behave as a transcriptional driver of SQLE expression in breast and ovarian cancer, as anticipated by the absence of MYC promoter elements upstream of SQLE40." (PMID 26777065, 2016). "The example of MYC, not strongly expressed in our data but previously shown to have a functional effect in ovarian cancer cell lines, clearly indicates that our approach should be considered complementary to others such as functional screens and deep sequencing of primary cancer samples." (PMID 20386695, 2010). "However, we failed to verify BUD31 is a direct target of MYC in ovarian cancer." (PMID 36271053, 2022). "Interestingly, a recent study showed that metformin inhibits the formation of tumor spheroids by ovarian cancer cells through a mechanism involving an increased FOXO3 nuclear localization and a consequent inhibition of the expression of several stemness markers, including Nanog, Oct-4 and c-MYC." (PMID 29389895, 2018). "In addition, c-MYC expression has been most often proposed as a general feature of the CSCs of various cancers including breast, prostate, esophagus and tongue, and the expression of c-MYC together with NANOG has been previously noted as a feature in a population of ovarian cancer cells." (PMID 30518424, 2018). "This suggests that BCAT1 may be a direct transcriptional target of c-MYC and an effector through which c-MYC exerts its oncogenic influence, a relationship that has previously been demonstrated in nasopharyngeal carcinoma, but needs to be explored in ovarian cancers." (PMID 25572314, 2015). "However, down-regulation of c-MYC has not been described previously in ovarian carcinoma cells." (PMID 24928374, 2014). "Although these studies were not in cancer cells, the current results support that MYC and HSF1 also form a protein complex in ovarian cancer cells and MYC-driven ovarian cancer cells are dependent on HSF1." (PMID 39831777, 2025).
ovarian carcinoma (continued). "As shown here, CAOV4 ovarian cancer cells, which overexpress MYC, display increased levels of rRNA transcription (assessed as pre-rRNA) and upregulation of “Pol I regulon” genes relative to CAOV3 ovarian cancer cells, which do not overexpress MYC." (PMID 29435159, 2018).